TXNL1P1 (thioredoxin like 1 pseudogene 1)
Gene: Processed pseudogene on chromosome 13 (86,725,500 to 86,726,053, forward strand). Ensembl gene ENSG00000231879.
Diseases named in the same sentence as TXNL1P1 in open-access papers:
TXNL1P1 is named in the same sentence as 1 disease in open-access papers, as found by Europe PMC text mining. Sharing a sentence is not in itself a finding about the gene and the disease. The quoted sentences say what the papers report.
Hypertension (1 paper, 2023). The presence of chronic increased pressure in the systemic arterial system. "However, the mechanism of other genes, such as TXNL1P1, PIP5K1C, MIR3147, and SLC47A1, underlining hypertension requires further investigation." (PMID 36869404, 2023).